LAG3 (lymphocyte activating 3)
Diseases named in the same sentence as LAG3 in open-access papers (continued):
Sharing a sentence is not in itself a finding about the gene and the disease.
melanoma (continued). "Modulating the expression of immune checkpoint receptors such as PD-1, TIM-3, and LAG-3 on melanoma cells can affect cancer by altering the interactions between the cancer cells and the immune system." (PMID 37895833, 2023). "Across human cancers, melanoma samples exhibited the highest number of LAG3+ TILs, including LAG3+ NK cells, LAG3+ Tregs, and LAG3+CD8+ effector memory T cells." (PMID 36719749, 2023). "As LAG‐3 inhibitors gain popularity in the clinical world to treat melanoma, more adverse effects have been reported." (PMID 38047262, 2023). "We had previously observed a reduced expression of LAG3 in melanoma tissue from patients with type 2 diabetes." (PMID 37880788, 2023). "In an autologous TILs/melanoma co-culture system, concurrent anti-PD-1/LAG-3 treatment improves tumor control via numerically increasing the CD8+T-cells and significantly raising the T cell/melanoma cell ratio." (PMID 37345056, 2023). "Concurrently, the LAG-3/PD-1 dual-antibody EMB-02 treatment plan for melanoma has been approved, suggesting that the treatment of TNBC through dual-antibody combined chemotherapy warrants further investigation." (PMID 37762493, 2023). "Overall, these findings indicate that LAG-3 is now established as the third targetable immune checkpoint in melanoma." (PMID 36674809, 2023). "What is already known on this topic:LAG3 expression is reduced in melanoma tissue from patients with type 2 diabetes." (PMID 37880788, 2023). "Until last year, the second-generation checkpoint inhibitor Opdualag (targeting LAG-3) was just launched, and it was classified as a first-line treatment for unresectable melanoma along with the PD-1 inhibitor nivolumab." (PMID 37600822, 2023). "Additional research is required with regard to the demographics of patients who experience cutaneous adverse effects when specifically treated with LAG‐3 inhibitors for melanoma." (PMID 38047262, 2023). "In melanoma, LAG-3 is often overexpressed, which can inhibit the immune response via the suppression of T-cell activation and cytokine secretion, making the tumor more difficult for the organism to repress." (PMID 37895833, 2023). "The most recently accepted immune modulation agent inhibits LAG-3 (lymphocyte-activation-gene-3), which, in combination with nivolumab, provided a further therapeutic response in melanoma." (PMID 37568785, 2023). "Our results showed that high expression of LAG3 mRNA was associated with a better prognosis in terms of OS and PFS in patients with melanoma, consistent with previous report." (PMID 38062416, 2023). "Recently, our group conducted a gene profiling study of samples from peripheral blood of melanoma patients treated with ipilimumab, and found that patients with type 2 diabetes (T2D) had a lower expression of LAG3." (PMID 37880788, 2023). "This also introduced LAG-3 as the third immune checkpoint in the landscape of melanoma immunotherapy." (PMID 37484526, 2023). "It was found that the association between LAG3 and the LSECtin ligand inhibits the generation of IFN by effector T cells that are antigen-specific in melanoma cells." (PMID 37842234, 2023). "Our results show that increased expression of ITGAL is associated not only with PD1 and CTLA4, but also with other potential melanoma checkpoints (LAG-3, Tim-3, and TIGIT)." (PMID 37388230, 2023). "Antagonist anti-LAG-3 antibodies have been the mainstay of studies interested in releasing the brakes of the immune system in melanoma." (PMID 37484526, 2023). "What this study adds: The low expression of LAG3 is associated with reduced survival of patients with metastatic or unresectable melanoma and type 2 diabetes treated with LAG3 inhibitor." (PMID 37880788, 2023). "The combination nivolumab plus anti-LAG3 relatlimab, clearly superior to nivolumab alone in untreated melanoma according to the phase III trial RELATIVITY-047, is being evaluated in metastatic STS by a phase II study (NCT04095208)." (PMID 37190214, 2023).
melanoma (continued). "Melanoma cells that express MHC class II attract tumor-specific CD4+ T cells through their interaction with LAG3, resulting in impairing CD8+ T cell responses." (PMID 37842234, 2023). "We analyzed TCRβ-Seq (anti–LAG-3+anti–PD-1–treated melanoma n = 34, 86 samples; healthy donors n = 783) and scRNA+TCRαβ-Seq (n = 6, 18 samples) data to understand the antigen restriction of expanded T cells." (PMID 36719749, 2023). "In fact, dual genetic knockout of both LAG-3 and PD-1, in murine melanoma models, resulted in delayed growth of the tumor and increased survival of mice." (PMID 37484526, 2023). "Fifty-three patients with unresectable Stage III or Stage IV melanoma treated with anti-LAG-3 in combination with anti-PD-1 ± anti-CTLA-4 were included in this study." (PMID 37808404, 2023). "A different approach was taken for the development for the anti-LAG3 relatlimab where a combined phase II-III registration study was designed in first-line melanoma with a predefined futility analysis for activity in the phase II part." (PMID 37638048, 2023). "Immune cells in patients with melanoma have the highest expression of LAG3 in a pan-cancer analysis." (PMID 36719749, 2023). "Lymphocyte-activation gene 3 (LAG3) is an immune checkpoint receptor; novel LAG3 immune checkpoint inhibitors (ICIs) exhibit therapeutic activity in melanoma." (PMID 38062416, 2023). "They validated the option of LAG-3 blockade, in combination with PD-1 inhibitor, as a therapeutic option for patients with melanoma." (PMID 37484526, 2023). "The establishment of an immunosuppressive microenvironment is also mediated by the upregulation of the inhibitory immune checkpoints (PD-L1/PD-1, CTLA-4, TIGIT, LAG-3) by melanoma cells or those of the surrounding microenvironment." (PMID 36768978, 2023). "Fianlimab (REGN3767, anti-LAG3) is being tested in combination with cemiplimab (anti-PD-1) in a phase I dose-escalation study (NCT03005782) in advanced melanoma patients and showed clinical activities." (PMID 37928556, 2023). "The findings of addition of relatlimab to the immunotherapy backbone in melanoma shall accelerate other research studies to investigate further these patient populations and to better understand LAG-3-directed therapy combinations." (PMID 37484526, 2023). "In vivo studies have shown that LAG-3+ pDCs infiltrate the melanoma environment and interact with HLA-DR-expressing tumor cells." (PMID 36077354, 2022). "In this melanoma sample, expression of genes associated with the terminally differentiated phenotype of CD8+ T cells, such as HAVCR2 (TIM-3), LAG3, CXCL13, and GZMB, was highest in the tumor parenchyma adjacent to inflammation." (PMID 35584630, 2022). "The synergistic effect of the dual PD-1/LAG-3 blockade has been tested in preclinical models and in a recent global Phase 2–3 trial in patients with melanoma." (PMID 36230538, 2022). "Anti–LAG-3 plus anti–PD-1 therapy prolonged PFS in patients with advanced melanoma compared with anti–LAG-3 and anti–PD-1 alone in a phase III melanoma trial." (PMID 36225938, 2022). "In a Phase I/II study (NCT0198609) evaluating the safety and efficacy of anti-LAG-3 antibody in combination with anti-PD-1 antibody, 61 melanoma patients in a Phase I/II study well tolerated with an ORR of 11.5%." (PMID 35874717, 2022). "First, relatlimab, an antibody blocking the inhibitory immune checkpoint LAG-3, was approved in 2022 for the treatment of metastatic or unresectable melanoma in combination with nivolumab." (PMID 36358601, 2022). "Patients with PD-/LAG3 expressing melanoma whose disease had become refractory to anti PD-1/PD-L1 treatment responded better to combination of Nivolumab with Relatimab, a LAG3 targeting monoclonal antibody." (PMID 35054292, 2022). "Recently, the benefit of combining nivolumab and relatlimab, a new ICI that blocks the lymphocyte-activation gene (LAG-3), has been shown in patients with advanced melanoma." (PMID 35721217, 2022).
melanoma (continued). "The use of relatlimab (anti-LAG3) seems promising based on results obtained in melanoma and an interesting randomized phase II study is ongoing in NSCLC (NCT04623775)." (PMID 35515125, 2022). "Immunotherapy agents targeting LAG-3 have shown promise in melanoma and are undergoing evaluation in mRCC." (PMID 36291789, 2022). "In this sense, the combination of the LAG-3-blocking antibody relatlimab and nivolumab has recently revealed a greater benefit in metastatic or unresectable melanoma in the phase II to III RELATIVITY-047 trial." (PMID 36568253, 2022). "LAG–3 blockade (relatlimab) has been shown to be beneficial when combined with nivolumab for advanced melanoma." (PMID 36532038, 2022). "This combination includes Relatlimab (anti-LAG-3 mAb) and Nivolumab (anti-PD-1 mAb), targeting both the LAG-3 and PD-1 for the treatment of unresectable advanced melanoma." (PMID 36135216, 2022). "Studies in which LAG3 is targeted, mostly in combination with other IC inhibitors, are currently conducted for several tumor types such as melanoma, multiple myeloma (NCT04150965), colon cancer (NCT03978611) or lung cancer (NCT04623775)." (PMID 36376922, 2022). "Tawbi reported recently early results of relatlimab, a lymphocyte-activation gene 3(LAG-3)-blocking antibody, and nivolumab versus nivolumab alone in untreated advanced melanoma (RELATIVITY-047trial)." (PMID 35902427, 2022). "The expression of LSECtin and its interaction with the LAG-3 molecule are shown on B16 melanoma cells." (PMID 36140182, 2022). "Recently, relatlimab, an anti-LAG-3 antibody, was approved to treat melanoma in combination with nivolumab." (PMID 36551910, 2022). "Other combinations of inhibitors, such as anti-PD-1 plus LAG3 blockade, have reached a 16% objective response rate and 45% disease control rate in melanoma patients following progression after prior PD-1 blockade." (PMID 36675674, 2022). "It is the target of different drugs including relatlimab, an anti-LAG3 antibody recently approved by FDA for clinical use in melanoma, in combination with nivolumab." (PMID 36224560, 2022). "A clinical trial showed that LAG3-blocking antibody has synergistic effects with conventional immune checkpoint inhibitors for melanoma." (PMID 36499102, 2022). "The combination of relatlimab, a LAG-3-blocking antibody, and nivolumab has been shown to be safe and to have antitumor activity in patients with previously treated melanoma." (PMID 35874717, 2022). "More recently the combination of an anti-LAG-3 antibody with nivolumab for use in patients with melanoma added new hopes to this approach." (PMID 36387154, 2022). "In patients with various melanomas, LAG-3 co-expression with PD-1 correlates with a state of T cell dysfunction." (PMID 36077354, 2022). "The interaction between LSECtin and LAG-3 promotes tumor growth through suppression of anti-tumor T cell response in melanoma cells." (PMID 35958563, 2022). "Recently, the FDA has approved relatlimab, a checkpoint inhibitor that targets lymphocyte-activation gene 3 (LAG-3), for the treatment of melanoma." (PMID 36215234, 2022). "A further type of ICI, acting through the inhibition of lymphocyte-activation gene 3 (LAG-3), has shown promising results in melanoma and is under investigation for HCC." (PMID 36230538, 2022). "In humans, the presence and abundance of TRM is associated with improved prognosis in patients with melanoma, TRM isolated from human melanoma specimens display high PD-1 and LAG-3 expression corroborating pre-clinical models." (PMID 36466880, 2022). "Preliminary efficacy data of relatlimab (a human IgG4 LAG-3-blocking antibody) and nivolumab in patients with melanoma that progressed while on or after treatment with anti-PD1 or anti-PDL1 therapy were presented in 2017." (PMID 35053435, 2022). "Following RNA-sequencing analysis and IHC on a series of anti–PD-1–treated melanoma and non–small cell lung cancers, LAG-3 expression was upregulated." (PMID 35037899, 2022).
melanoma (continued). "Melanoma patients treated with the combination of anti-LAG3 antibody Relatlimab and anti-PD-1 antibody Nivolumab have median progression-free survival of 10.1 months compared with 4.6 months with Nivolumab alone." (PMID 36499102, 2022). "In melanoma, LAG3 can bind to MHC-IIs upregulated on tumor cells, upregulating MAPK/Erk and phosphatidylinositol-3-kinase (PI3K)/Akt pathways to confer melanoma cells resistance to Fas-mediated and drug-induced apoptosis." (PMID 35345849, 2022). "Relatlimab was the first anti-LAG-3 mAb that entered clinical testing, as a monotherapy or combination therapy with nivolumab, an anti-PD-1 mAb, in melanoma, renal cell carcinoma, and non–small cell lung carcinoma (NCT019680109)." (PMID 33712537, 2021). "The anti-LAG-3 antibody (relatlimab) is currently being evaluated in first-line advanced melanoma and has demonstrated progression free survival benefit when added to anti-PD-1 antibody (nivolumab)." (PMID 34356465, 2021). "Among these diseases, melanoma shows a close relationship between the coexpression of the immune checkpoint molecules LAG3 and PD-1 and the expression of CD163 and density of TAMs." (PMID 34526102, 2021). "A pre-clinical study reported that MHC class II engagement by its ligand LAG-3 contributes to melanoma resistance to apoptosis." (PMID 34771650, 2021). "In this regard, early results in a clinical trial with LAG-3 inhibitors showed promising results in patients with advanced melanoma with resistance to PD-1 blockers." (PMID 34572874, 2021). "In vivo data demonstrate that the single knockout of PD-1 or LAG-3 in mice shows a subtle and limited result whereas the blockade of dual LAG-3/PD-1 reveals a clear synergy between these two molecules with a significant melanoma and colon tumor regression." (PMID 34572799, 2021). "Lymphocyte-activation gene 3 (LAG-3) expression is increased on human plasmacytoid DCs isolated from melanoma metastasizing to the lymph node and skin." (PMID 32902664, 2021). "The engagement of LAG-3 with MHC II expressing on melanoma cells impedes apoptosis of these tumor cells and provokes metastasis." (PMID 32902664, 2021). "In one study, LSECtin was expressed on murine B16 melanoma cells: interaction between LSECtin and LAG3 led to inhibition of Interferon γ (IFNγ) secretion by CD8 T cells and reduced their cytotoxic activity, promoting tumour growth." (PMID 34503258, 2021). "Initial results with the anti-LAG-3 antibody relatlimab combined with nivolumab showed a nearly 3-fold higher response rate among patients with melanoma whose tumors expressed LAG-3 ≥ 1% versus those who had <1% LAG-3 expression (20% vs. 7.1%)." (PMID 35008245, 2021). "Currently, multiple clinical trials evaluating the synergistic effects of anti-LAG3 and anti-PD-1 antibodies are ongoing, and significant efficacy has been achieved in completed trials on melanoma (stage III/IV), metastatic breast cancer and RCC (stage IV)." (PMID 34526102, 2021). "Recent studies have demonstrated that LAG-3 blockade prevents Treg recruitment and promotes DCs function in melanoma treatment." (PMID 34806028, 2021). "At present, numerous clinical trials investigate the efficacy of LAG3 blockage, enrolling patients with a broad spectrum of neoplastic diseases (e.g., head and neck carcinomas, melanoma, colorectal carcinoma, NSCLC: NCT01968109)." (PMID 32232506, 2020). "LAG-3 expression has been shown on a subset of pDCs in healthy individuals as well as on pDCs in melanoma patients with a clear enrichment in LAG-3+ pDCs in melanoma-invaded lymph nodes and in cutaneous melanoma metastasis." (PMID 33374804, 2020). "We demonstrated significant inverse correlations of LAG3 mRNA expression with methylation of CpG sites in 12 out of 16 analyzed beads in the TCGA malignant melanoma cohort that were mainly located in the promoter region of the LAG3 gene." (PMID 32861198, 2020).
melanoma (continued). "Based on our results, we suggest following up on LAG3 DNA methylation as a biomarker in melanoma patients and to test the predictive value of LAG3 DNA methylation in patients treated with LAG3 targeted antibodies." (PMID 32861198, 2020). "We validated melanoma cell-intrinsic LAG3 expression and a transcriptional regulation via DNA methylation in the established melanoma cell line A375." (PMID 32861198, 2020). "LAG3 expression was also found on melanoma infiltrating plasmacytoid DCs which contributed to an immunosuppressive microenvironment." (PMID 32861198, 2020). "Knowledge on tumor cell-intrinsic mRNA expression of LAG3 in melanoma and its transcriptomic regulation is scarce." (PMID 32861198, 2020). "We found significant correlations between LAG3 methylation and mRNA expression with lymphocyte score, signatures of tumor infiltrating lymphocytes, IFN-γ signature, and survival, suggesting a prognostic and predictive significance of LAG3 in melanoma." (PMID 32861198, 2020). "Further supporting a role of obesity-induced T cell exhaustion in melanoma is the increase in gene expression of inhibitory molecules PD-1, TIGIT, EOMES, TIM3 and LAG3 found in melanoma patients with a high body mass index (BMI)." (PMID 32549336, 2020). "In this study, we investigated the correlation between the density of M2-TAMs and the immune checkpoint molecules PD-1 and LAG-3 by using immunohistochemistry on melanoma tissue." (PMID 32756500, 2020). "Our study points towards an epigenetic regulation of LAG3 via promoter methylation and suggests a prognostic and predictive significance of LAG3 methylation in melanoma." (PMID 32861198, 2020). "In a phase I/IIa study, the anti-LAG-3 antibody BMS-986016 was used in combination with nivolumab (NCT01968109) in patients with relapsed melanoma treated with anti-PD-1 antibodies." (PMID 32461587, 2020). "In a next step, we investigated LAG3 methylation in melanocytes and melanoma cell lines and in isolated peripheral blood mononuclear cells (PBMCs), comprising lymphocytes and monocytes." (PMID 32861198, 2020). "A comparison of melanoma samples derived from patients pre and post anti-PD-1 treatment revealed increased frequencies of LAG3+ TILs as a function of developing adaptive resistance in paired specimens." (PMID 33162991, 2020). "Preliminary data from a phase 1/2 study in melanoma patients showed the combination of nivolumab with BMS-986016 (IgG4 antibody targeting LAG3) had similar safety profile to nivolumab monotherapy, with encouraging efficacy." (PMID 33327433, 2020). "In a phase I/IIa study, the anti-LAG-3 antibody BMS-986016 was applied in combination with nivolumab in patients with malignant melanoma who previously developed progressive disease on PD-1 blockage." (PMID 33396515, 2020). "Similar to our result, high expression of LAG-3 predicted poor survival in head and neck squamous cell carcinoma, melanoma, soft tissue sarcomas and non-small cell lung cancer (NSCLC)." (PMID 32762721, 2020). "In our previous study, LAG-3 expression correlated with PD-1 expression in melanoma, potentially acting as a prognostic biomarker." (PMID 32756500, 2020). "High levels of LAG3 have been found on immunosuppressive Tregs in cancer patients, e.g. in melanoma and colorectal carcinoma." (PMID 32861198, 2020). "LSECtin is expressed in melanoma and liver cancer cells, suggesting a process that allows LAG3 to regulate NK cells and CD8+ T cells in TME." (PMID 33167514, 2020). "In melanomas and colorectal cancer, LAG3 is predominantly expressed on FOXP3+ regulatory T cells that exert an immunosuppressive function through release of TGF-ß and IL10 in the TME." (PMID 32232506, 2020). "So far, knowledge about epigenetic regulation of LAG3 and tumor cell-intrinsic expression of LAG3 in melanoma is scarce." (PMID 32861198, 2020). "Accordingly, Tregs have been shown to express LAG3 in dynamic levels, depending on the state of activation, and with high levels described in melanoma." (PMID 32861198, 2020).